CASP1 (caspase 1)
Diseases named in the same sentence as CASP1 in open-access papers (continued):
Sharing a sentence is not in itself a finding about the gene and the disease.
Insulin resistance (40 papers, 2013 to 2025). Increased resistance towards insulin, that is, diminished effectiveness of insulin in reducing blood glucose levels. "Genes with a positive association with inflammation, chemotaxis, insulin resistance, and inflammatory cell death, such as Irf5, Alox5ap, Tlrs, Cd84, Ccr5, Ccl9, and Casp1, were downregulated by EPA." (PMID 32906847, 2020). "Its documented suppression of the TLR4/NF-κB and NLRP3/caspase-1 axes directly counteracts the chronic low-grade inflammation that underpins insulin resistance." (PMID 41459066, 2025). "Using SGBS cells and murine in vitro models, Caspase 1 has been previously identified as a key mediator of IL-1β-driven insulin resistance." (PMID 35986215, 2022). "With the discovery that NLRP3 inflammasome mediates caspase-1 activation and IL-1β maturation, its relation with insulin resistance and type 2 diabetes development has been recognized; NLRP3 deficiency protects mice from obesity-induced insulin resistance." (PMID 36741414, 2022). "The enhanced secretion of pro-inflammatory cytokines during adipocyte hypertrophy occurs via the activation of the caspase-1/inflammasome and contributed to insulin resistance in several mice models (IL-1β-/-, Caspase-1-/-, NLRP3-/-, db/db, and ob/ob mice)." (PMID 34654807, 2021). "Casp1 expresses Caspase 1, which governs the production of the pro-inflammatory cytokine IL1β, playing a role in the development of insulin resistance." (PMID 31614949, 2019). "The NLRP3 inflammasome activity promotes insulin resistance and genetic deficiency in NLRP3 inflammasome, ASC or caspase-1 ameliorates insulin signaling pathway in obese mice." (PMID 28765650, 2017). "New data shows that high-fat diet feeding-induced caspase-1 can deactivate Sirt1 and leads to insulin-resistance." (PMID 23483669, 2013). "The resulting activation of caspase-1 and subsequent secretion of IL-1β then interfere with insulin signaling, whereas inhibition of caspase-1 has been demonstrated to attenuate insulin resistance coincident with improved function of adipocytes." (PMID 23964268, 2013). "The caspase-1 associated pathways in lipid metabolism include, along with interleukins, SREBS (and lipid biosynthesis), FABS (and lipid absorption and VLDL secretion), SIRT1 (and adipogenesis and insulin resistance), and others." (PMID 34502478, 2021). "NLRP3 is a protein responsible for the regulation of immune inflammation, and its activation can trigger the activation of caspase-1 and the production of inflammatory mediators, ultimately leading to apoptosis of β-cells in the pancreatic islets, leading to insulin resistance." (PMID 32774321, 2020). "The activation of caspase-1 enhances the secretion of IL-1β from adipose tissue in GDM and triggers the development of insulin resistance." (PMID 31558153, 2019). "AC-YVAD-CMK treatment markedly decreased caspase-1 activity, serum IL-1β, blood glucose, fasting serum insulin levels, and HOMA, an indicator of insulin resistance." (PMID 31387986, 2019). "Our study showed that WMW inhibited IL-1β production and relieved insulin resistance in palmitate-treated HepG2 cells via reduction of the expression of the three components of NLRP3 inflammasome: NLRP3, ASC, and caspase-1 (p20)." (PMID 28928791, 2017). "In fact, curcumin, polydatin, quercetin, and hesperetin can increase the levels of the pro-osteogenic markers COL1A1 and ALP and inhibit the catalytic activity of the enzymes caspase 1 and DPPIV, which play a fundamental role in the development of the insulin resistance condition in T2DM." (PMID 39062550, 2024). "Furthermore, LrB can reduce inflammation and insulin resistance in individuals with PCOS by inhibiting NLRP3, Caspase-1, TNF-α, IL-6, IL-1β, and IL-18 and increasing the expressions of GPR120, LKB1, and AMPK." (PMID 39456928, 2024).
Insulin resistance (continued). "Activated NLRP3 inflammasome and downstream caspase-1 do not affect the ratio of M1/M2 in adipose tissue but promote the secretion of IL-1β and IL-18, leading to insulin resistance." (PMID 35757707, 2022). "In addition, these mice display increased inflammation in skeletal muscle as demonstrated by higher levels of IL-1β, caspase-1 and NLRP3, probably explaining the increased insulin resistance in these mice." (PMID 26405763, 2015). "In addition, several studies using genetically modified mice that lack inflammasome components NLRP3, ASC, and Caspase-1 provided initial evidence that activation of the NLRP3 inflammasome is a key mechanism that induces metabolic inflammation and insulin resistance." (PMID 36232419, 2022).
ischemic stroke (39 papers, 2014 to 2026). A stroke disorder caused by obstruction of blood flow to the brain, due to thrombotic (local blood clot formation) or embolic (due to a blood clot or other material traveling from another site) event. "The neuroprotective mechanisms are associated with regulations of TLR4/NF-κB/NLRP3/ caspase-1 and caspase-3 signals, as well as Bcl-2/Bax ratio, suggesting SO is a novel neuroinflammatory regulator in ischemic stroke." (PMID 40289983, 2025). "This strongly underlines the role of caspase-1 in cell death after ischemic stroke." (PMID 33584203, 2020). "Our data shows that ISO pretreatment can downregulate NLRP3, caspase-1, and IL-1β mRNA and protein levels in the retina after ischemic stroke, suggesting that the protective mechanisms underlying ISO pretreatment may be related to the direct inhibition of retinal NLRP3 inflammasome activation." (PMID 34305534, 2021). "This study underscores the significant therapeutic potential of the herbal mixture Astragalus mongholicus (AM) and Scutellaria baicalensis (SB) in mitigating inflammation and pyroptosis via modulation of the NLRP3/Caspase-1/GSDMD pathway in ischemic stroke." (PMID 39859214, 2025). "As expected, TXNIP knockdown reduced the levels of NLRP3, ASC, pro-caspase-1, and IL-1β proteins, indicating that TXNIP’s role in ischemic stroke is associated with the NLRP3 inflammasome pathway." (PMID 39690856, 2025). "The nucleotide-binding oligomerization domain-like receptor protein 3 (NLRP3) and the caspase-1-mediated pyroptosis pathway play pivotal roles in ischemic stroke-induced brain injury." (PMID 39690856, 2025). "Caspase-1 contributes to inflammation in ischemic stroke by processing the pro-inflammatory cytokine IL-1β into its active form." (PMID 39625520, 2024). "Its increased density is a measure of microglial activation, which is also manifested by overstimulated caspase-1 activity and elevated levels of interleukins in the brain during ischemic stroke." (PMID 38949694, 2024). "Pyroptosis, a form of programmed cell death initiated by the generation of the NLRP3 inflammasome, which promotes caspase 1 activation, is involved in the initiation and development of ischemic stroke." (PMID 37681864, 2023). "In our study, the levels of inflammatory factors including NLRP3, Caspase-1, and IL-1β were elevated in the MCAO group, demonstrating that the NLRP3 inflammasome was associated with the development of ischemic stroke." (PMID 36262547, 2022). "Caspase-1 expression was considerably enhanced after ischemic stroke as a critical molecule in initiating pyroptosis, and its suppression resulted in neuroprotection against I/R injury." (PMID 35136042, 2022). "Extensive caspase-1 immunoreactivity was observed in the vehicle group 28 days following ischemic stroke." (PMID 36441377, 2022). "It is reported that ischemic stroke enhances pyroptosis markers including caspase-1/11, and inhibition of caspase-1 is neuroprotective." (PMID 35431804, 2022). "Caspase-1, an inflammasome-activated NLRP3 enzyme capable of lysing other proteins, is also implicated in the pathophysiology of ischemic stroke." (PMID 36297283, 2022). "Our findings provide evidence that the administration of a caspase-1 inhibitor can protect against secondary degeneration after ischemic stroke." (PMID 36441377, 2022). "We found that the serum concentration of NLRP3 was positively correlated to CASP1, providing preliminary clinical evidence to the involvement of pyroptosis in ischemic stroke." (PMID 34493232, 2021). "The study further explored mechanisms underlying caspase-1-induced BBB damage, as well as the precise pathology of ischemic stroke." (PMID 33584203, 2020).
ischemic stroke (continued). "Accordingly, ischemic stroke was found to significantly increase the levels of cleaved caspase-1, ASC, NLRP3, cleaved GSDMD, IL-1β, and IL-18." (PMID 33584203, 2020). "In the ischemic stroke model, inhibition of caspase-1 or caspase-1 knockout reduced cerebral infarction damage and significantly protected brain injury." (PMID 33584203, 2020). "Inflammasome can mediate neurocytes death in ischemic stroke via a number of mechanisms, including the productions of pro-inflammatory factors and the pleiotropic effects of cleaved caspase-1 in mediating apoptosis and pyroptosis." (PMID 31416289, 2019). "Therapeutic hypothermia suppresses the abnormal activation of CDK5 in neurons following ischemic stroke, which results in a reduction in NF-κB activity and inhibition of caspase 1, ultimately decreasing the caspase 1-dependent production of IL-1β." (PMID 31644666, 2019). "Previous studies in ischemic stroke have demonstrated that exogenous IL-1 administration can exacerbate neuronal injury, while inhibition of caspase-1 or IL-1 receptor provides protection." (PMID 27199506, 2016). "In ischemic stroke, multiple inflammasomes (NLRC4, NLRP1, NLRP3, NLRP6, AIM2) have been implicated, with AIM2 uniquely recognizing cytosolic dsDNA to drive AIM2-ASC-caspase-1 complex formation and GSDMD-mediated pyroptosis." (PMID 41344159, 2025). "The NLRP inflammasome is a key tripartite multi-protein composite that contains the nucleotide-binding oligomerization domain (NOD), C-terminal caspase-recruitment domain (CARD), and activated caspase-1 that regulates inflammatory response and neuronal pyroptosis in ischemic stroke." (PMID 37915409, 2023). "Indeed, treatment of Caspase-1/-11 inhibitor after ischemic stroke offered favorable neuroprotection." (PMID 33967935, 2021). "NLRP3 inflammasomes can regulate glial and neuronal cell death in ischemic stroke via enhancing generation and secretion of the pro-inflammatory cytokines including IL-1β and IL-18 and through pleiotropic impacts of cleaved-caspase-1 in regulating neuronal cell apoptosis." (PMID 32581721, 2020). "Expression of caspase-1 significantly increases in neurons after ischemic stroke." (PMID 33584203, 2020). "NOX inhibitor apocynin and nicotinamide adenine dinucleotide phosphate (NADPH) could inhibit the level of NLRP3, ASC, caspase-1, IL-1β and IL-18 in the cortex, improve the neurological functions, and decrease the infarct volume in ischemic stroke mouse model." (PMID 32581721, 2020). "As the first identified inflammasome in cerebral ischemic injury, NLRP1 inflammasome could activate precursor caspase-1 to produce both mature IL-1β and IL-18 to mediate neurocytes death after ischemic stroke." (PMID 31416289, 2019). "Another study also found that Tranilast, an NLRP3 inflammasome inhibitor, could promote the polarization of microglia/macrophage from M1 type to M2 type and ameliorate ischemic stroke by inhibiting the NLRP3/caspase-1 pathway in a murine model of distal middle cerebral artery occlusion." (PMID 36035210, 2022). "Therefore, studies in the literature support the hypothesis that caspase-1 plays a crucial role in the pathogenesis of ischemic stroke." (PMID 36297283, 2022). "Therefore, we explored whether suppressing Caspase-1 or−11 signaling could inhibit inflammasome activation in macrophages and its therapeutic effects in ischemic stroke." (PMID 33967935, 2021). "Notably, in our previous study of human peripheral blood leukocytes following ischemic stroke, we also observed sexually dimorphic cell death pathways with females showing Caspase 1, HMGB1, and NFkB Signaling pathways, while in males Granzyme A signaling and other cell death molecules were involved." (PMID 25036109, 2014). "This study planned to mainly evaluate the effects of AS-IV and HSYA on NLRP3 inflammasomes after ischemic stroke and further elucidate the anti-pyroptotic effects via the NLRP3/Caspase-1/GSDMD pathway." (PMID 39199474, 2024).
ischemic stroke (continued). "It has also been observed to reduce pyroptotic proteins such as cleaved-caspase-1, GSDMS-N, and IL-1β following ischemic stroke." (PMID 37915409, 2023). "In the wake of ischemic stroke, increased DAMPs from injury cells and stimulated NLRP3 protein bind to the adapter protein ASC and pro-caspase-1, subsequently triggering the maturation of precursors IL-1β and IL-18 to induce neuroinflammation." (PMID 37915409, 2023). "In this study, we demonstrated that the ischemic stroke-induced activation of NLRP3 was significantly reduced by MFSCE, as so were the downstream targets of cleaved caspase-1 and caspase-11, mature IL-1β, and IL-18." (PMID 35454994, 2022). "SYK inhibitor R406 significantly deactivated NLRP3, Caspase-1, and GSDMD-N signaling; reduced the concentration of IL-1β; and attenuated GSDMD-N induced membrane pores in mice with ischemic stroke." (PMID 33402173, 2021). "Diabetes can amplify NLRP3 and caspase-1 activation in rats after ischemia, which can mediate the facilitation of tPA-induced BBB damage and the tendency of HT in ischemic stroke." (PMID 35370546, 2022). "What is more, it was also reported that MCC950 improved neurological dysfunction at 24 h after cerebral I/R and promoted 28-day survival rate in diabetic mice with ischemic stroke, involving in the mRNA transcription level changes of NLRP3, caspase-1, and IL-1β." (PMID 32581721, 2020). "Besides, ruscogenin is a crucial steroid sapogenin derived from Ophiopogn japonicus, and ruscogenin could improve neurological dysfunctions of ischemic stroke mice via suppressing expression levels of NLRP3, IL-1β, caspase-1, TXNIP, MAPK, and ROS." (PMID 32581721, 2020).
liver fibrosis (38 papers, 2013 to 2025). "All of these results indicated that caspase-1 was involved in schistosomiasis-associated liver fibrosis." (PMID 31610797, 2019). "Previous studies have shown that the antifibrosis effect of a type of ginsenoside AD-2 extracted from ginseng on thioacetamide-induced liver injury in mice is related to the inflammatory factors (including TNF-α, IL-1β, caspase-1, and IL-6) associated with hepatic fibrosis." (PMID 32724321, 2020). "For instance, exosomes derived from bone marrow mesenchymal SCs mitigate liver fibrosis in cirrhosis rat models by inhibiting PCNA/NLRP3/caspase 1/GSDMD-mediated pyroptosis." (PMID 40667485, 2025). "It has been reported that the development of liver fibrosis in mice can be reduced by blocking one of the three NLRP3 inflammasomes (caspase-1, ASC, or NLRP3)." (PMID 40367564, 2025). "We identified the NLRP3/Cleaved Caspase-1/IL-1β signaling in the liver to evaluate the impact of MP-40 on hepatic fibrosis and to clarify the mechanism of action of MP-40 in treating hepatic fibrosis." (PMID 39372196, 2024). "Liu and colleagues found that liver expression of GSDMD, NLRP3, caspase-1 and IL-1β increased in Schistosoma japonicum-infected mice, leading to exacerbation of hepatic fibrosis." (PMID 38086792, 2023). "MCC950, an agent that can block NLRP3 inflammasome, decreases the expression of liver caspase-1 and the numbers of macrophages and neutrophils, ultimately alleviating liver fibrosis." (PMID 32211410, 2020). "Activated caspase-1, IL-18, and IL-1β signaling are also pivotal to the development of liver fibrosis resulting from the activation of NLRP3 inflammasome." (PMID 32211410, 2020). "Nevertheless, NLRP3 inflammasome acts indirectly on the adaptative immune system by stimulating caspase-1 and IL-1β production, which favor Th17 cell differentiation and secretion of IL-17, resulting in continuous liver fibrosis state." (PMID 32085494, 2020). "From small molecule compounds targeting caspase-1 and Akt-1, compound 13 was selected for virtual screening with molecular modeling, molecular docking and MD simulations, for its effect of hepatic fibrosis." (PMID 26389883, 2015). "Previous studies have shown that the NALP3 inflammasome and NALP3-dependent caspase-1 activation are central to the inflammation and the development of the liver fibrosis." (PMID 25512222, 2014). "Given the recent findings of the inflammasome and caspase-1 in liver fibrosis, we evaluated the role of caspase-1 in high fat diet-induced early fibrogenesis." (PMID 23409132, 2013). "Hepatic fibrosis is accompanied by activation of Caspase-1 and Caspase-11 pyroptosis." (PMID 37005411, 2023). "However, macrophage-specific Atg5 knockout promoted caspase-1 activation, and pro-inflammatory M1 macrophage polarization, resulting in liver fibrosis during chronic ethanol exposure." (PMID 35707547, 2022). "Moreover, the caspase-1–IL-1β signaling pathway in macrophages leads to lipid accumulation, inflammatory infiltration, and liver fibrosis in NASH mouse models by mediating macrophage–hepatocyte and macrophage–HSC interactions." (PMID 35707547, 2022). "Furthermore, in vivo inhibition of NLRP3 inflammasome with caspase-1 inhibitor dramatically decreased mature IL-1β level of liver tissue and ameliorated liver fibrosis in bile duct ligation (BDL) mouse model." (PMID 27924062, 2016). "Common features of the top three pathways for KD (Trem1 signaling, Hepatic fibrosis, and IL-10 signaling) and the other groups were the abundance of transcripts related to the activation of the Nlrp3 inflammasome, including Il-1 and caspase-1 related transcripts." (PMID 25614765, 2014). "We also found significant upregulation of caspase 1 (Casp1), a key inflammation mediator; Janus kinase 3 (Jak 3), a key controller of signal transduction after receptor activation by the common γ chain; and platelet-derived growth factor (Pdgfb), a key regulator of hepatic fibrosis." (PMID 30305319, 2018).